BDNF (brain derived neurotrophic factor)
Diseases named in the same sentence as BDNF in open-access papers (continued):
Sharing a sentence is not in itself a finding about the gene and the disease.
depression (continued). "Quite unexpectedly, we found no notable change in accumbal BDNF levels in naive female depressive-like H mice, indicating that the increase in accumbal BDNF signaling observed in stress-induced models of depression should not automatically be extended to genetic animal models of depression." (PMID 25733538, 2015). "Thus, BDNF genetic studies of patients with and without depression may shed light on the potential genetic link between depression and T2DM." (PMID 23968401, 2013). "However, the relationship between BDNF and body weight in depression is not clear." (PMID 22768299, 2012). "Furthermore, studies analyzing gene-environment interactions reported that BDNF Met carriers exposed to early life stress events (ELS) have smaller hippocampal and amygdala volumes, heart rate elevations, a decline in working memory and higher depression symptoms." (PMID 20141627, 2010). "In addition, the depression vulnerability due to sedentary behaviours is closely related to alterations in brain metabolism, particularly changes in brain-derived neurotrophic factor (BDNF) levels, which is reported to have negative correlation with sedentary behaviours in related studies." (PMID 41286742, 2025). "People with major depressive disorder (MDD)have lower peripheral and central BDNF levels compared to non-depressedindividuals." (PMID 40352065, 2025). "Animal experiments have shown that hippocampus BDNF mRNA level increases and anxious behavioral experiments was significantly reduced when mice wheel exercise and regular PA could also increase the release of endorphin, thereby reducing depression, anxiety, and other negative emotion." (PMID 40732932, 2025). "Anxiety and depression-like behavior, impaired synaptic plasticity in the hippocampus, and decreased p-CREB and BDNF were not significantly reversed in adult PTSD mice treated with a single dose of NaHS." (PMID 40551819, 2025). "The study found weak negative correlations between IL-4, BDNF, and neopterin levels and changes in PHQ-9 scores at both TP2 and TP3, suggesting a potential inverse relationship between these markers and depression symptoms." (PMID 39355088, 2024). "It is possible that central BDNF levels, rather than serum BDNF, may be more closely correlated with mood disorders and suicidality, as studies have demonstrated lower BDNF levels in the prefrontal cortex and hippocampus of individuals with major depression and those who have died by suicide." (PMID 39474368, 2024). "We found that chronic fluoxetine treatment reversed depression‐like behavior after CSDS, but the knockout of BDNF in the LCTH‐dLS circuit did not block the antidepressant effect of fluoxetine." (PMID 38155473, 2024). "Therefore, it seems possible that the higher salivary levels of BDNF in students with more depressive symptoms were the expression of initial compensatory neuroprotective mechanisms; in fact, none of them suffered from clinically diagnosed depressive disorder, and none took antidepressant drugs." (PMID 38396487, 2024). "They further revealed a significant negative correlation between the self-rating depression scale (SDS) score and BDNF levels while showing a positive correlation between the SDS score and the serum mir-132 level." (PMID 37396946, 2023). "Baseline comparisons of adiponectin, resistin, and BDNF concentrations were not significantly different before and after ECT treatment in the entire patient group and subgroups distinguished by depression type, sex, or symptom improvement status." (PMID 37891727, 2023). "Whether or not serum levels of BDNF correlate with mouse models of depression, or indeed with any mouse model of CNS dysfunction, can now be investigated, given that the confounding factor resulting from the presence of platelet-derived BDNF is absent in the mouse." (PMID 37470055, 2023).
depression (continued). "A recent meta-analysis reported the beneficial effect of regular leisure-time PA on the circulating brain-derived neurotrophic factor (BDNF) level, which is decreased in patients with depression, was significant only in women and not in men." (PMID 37397713, 2023). "An increasing number of studies have demonstrated that BDNF and VGF (nonacryonimic) proteins are decreased in animal models of depression." (PMID 36550125, 2022). "Responders (>50% improvement in the Beck Depression Scale, BDI) had a nonsignificant increase in BDNF protein levels, while poor responders (≤50% improvement in BDI) showed a nonsignificant decrease in protein levels." (PMID 34640441, 2021). "Within 91 pmTBI patients, neither the identified five methylation components nor the 13 CpG sites in BDNF and APOE4 genes were significantly related to the depression symptom score at EC visit." (PMID 34247653, 2021). "Further, lower BDNF levels are observed in the PFC and the hippocampus of suicide victims compared to non-victims of suicide with or without depression." (PMID 34065586, 2021). "After dividing patients according to diagnoses into the depressive disorder subgroup (DD-S, n = 30) (DD without MADD) and mixed anxiety and depressive disorder (MADD, n = 25), only EPA but not DHA correlated positively with BDNF in patients in the DD subgroup." (PMID 33801688, 2021). "The results suggest lower BDNF and NCAM levels in patients with AUD with and without comorbid depression, compared to healthy controls." (PMID 32372985, 2020). "These aggravated symptoms were also normalized by a BDNF-TrkB blockade in the NAc, which showed that BDNF-TrkB signaling, rather than DA signaling in the VTA-NAc circuit, is crucial for facilitating depression-like outcomes after experiencing CSDS." (PMID 32694984, 2020). "BDNF had a negative correlation, while MDA and 8-OhdG had a positivecorrelation, with depression one-month post-stroke." (PMID 32206197, 2020). "Genetic associations were determined by sequentially regressing prolactin, BDNF, 17-items Hamilton's Depression (HAMD-17) and Clinical Global Impression scale, Severity (CGI-S) ratings, and depression (absent/present) on the available SNPs." (PMID 32116853, 2020). "Our study showed that overall BDNF, NGF, NT-3, and NT-4 levels are higher in METH users with depression compared to METH addicts without depression (d = 0.65, 0.59, 0.76, 0.78, respectively)." (PMID 32210759, 2020). "BDNF and Neuronal CAM were lower in patients with AUD with and without depression compared to healthy controls." (PMID 32372985, 2020). "In patients suffering from depression, soluble forms of ICAM-1 and VCAM-1 were increased, as opposed to reduced levels of BDNF." (PMID 32372985, 2020). "Levels of BDNF, hsCRP, IL-6 and TNF-α are able to discriminate either euthymia or depression by being no different in that mood phase in comparison with levels in controls but altered in other mood phases." (PMID 30113291, 2018). "We previously reported a marked reduction of BDNF-TrkB signaling in the PFC, DG, and CA3, but not CA1, of inflammation model of depression." (PMID 27844095, 2017). "In a clinical study, serum BDNF levels were significantly lower in MDD patients than in controls and depression severity mainly accounted for the negative correlation." (PMID 29348904, 2017). "On closer inspection of these results it appears that the childhood adversity-BDNF relationship in depression may be complex, with some studies reporting a significant interaction among women and not men, and for specific subtypes of depression (non-melancholic)." (PMID 24433458, 2014). "VGF (non-acronymic) and BDNF (brain-derived neurotrophic factor) whose transcriptions are dependent on CREB, involved in depressive disorders." (PMID 24401376, 2014).
depression (continued). "Therefore, although plasma BDNF may be a valuable biomarker for the treatment of depression, it may not be appropriate or feasible to establish a normal range (as is done for numerous other serum components to establish a baseline for assessing physiological status)." (PMID 22761741, 2012). "Change in the serum BDNF between weeks 0 to 12 was significantly larger in the non-distress group than in the distress group, who met the criteria for PTSD or major depression (median, 33.5; range, 8.5-56.0 vs. median, 5.4; range, 4.4-6.4, p = 0.037)." (PMID 21303552, 2011). "Furthermore, reduced levels of brain-derived neurotrophic factor (BDNF) methylation in CpG 5–11 have been found in subjects with tobacco use and depression compared to those who did not consume tobacco with or without depression." (PMID 39199463, 2024). "Although the present study did not assess BDNF genotypes, a significant decline in BDNF levels post-R-CHOP chemotherapy and an inverse relationship with PHQ-9 scores was noted suggesting the pathophysiological role of BDNF in chemotherapy-related depression." (PMID 39355088, 2024). "In patients with post-stroke depression, their serum BNDF level is lower than in those without depression, and antidepressants could enhance the BDNF expression in their brains." (PMID 37266540, 2023). "Notably, we found that the basal serum level of BDNF did not correlate significantly with symptom severity, PSD scores or fibromyalgianess, depression and pain severity regardless of the diagnosis (FM or non-FM NP)." (PMID 35501732, 2022). "Lower expression of BDNF have been present in the prefrontal cortex and hippocampus of post-mortem brain from subjects with major depressive disorder (MDD) without antidepressant treatment, and antidepressant could restore normal BDNF levels." (PMID 35873590, 2022). "There was a clear baseline difference of plasma BDNF levels, NGF levels, NT-3 levels, and NT-4 levels between the depression group and the nondepression group; however, the pro-BDNF plasma levels were not significantly different between these two groups (p = 0.830, d = −0.05)." (PMID 32210759, 2020). "Therefore, in this pilot study we measured levels of both BDNF and CAMs in patients with AUD with and without depressive disorder, and controls." (PMID 32372985, 2020). "However, the role of BDNF in CFS has not yet been determined, although it is a known biomarker of depression." (PMID 29643935, 2018). "Antidepressive and hippocampal BDNF effects persisted for 1 month without EET, indicating that early-life EET may prevent depression later in life." (PMID 27648918, 2016). "Increased S100B in males with minor depression, without alterations in BDNF and NSE, supports the glial hypothesis of depression." (PMID 26500502, 2015). "Moreover, MS180 evidently induced these depression-like effects; by contrast, MS15 did not significantly affect the BDNF and NF-L protein levels and the behavioral test results." (PMID 26798520, 2015). "In the present study, we hypothesized that the variability in serum BDNF levels was due to an absence of depression-related biological changes in MDD patients with weak SD, and this hypothesis was supported by the negative correlation between serum BDNF and SD." (PMID 25885038, 2015). "Thus, although the application of the Hamilton Depression Rating Scale (HDRS) scores did not detect significant gender differences, both healthy and depressed males showed higher serum BDNF levels than female subjects." (PMID 22654714, 2011). "However, not all studies in literature confirm the role of BDNF and CREB in depression and suicidal behaviour." (PMID 21441870, 2011). "Current evidence suggests that BDNF may be useful in predicting both MDD and the treatment response to traditional antidepressant medications; however, in treatment-resistant depression and with neuromodulatory treatments, BDNF may not be a good predictor of treatment response." (PMID 41440970, 2025).
depression (continued). "Of note, neither DA nor BDNF signaling in the VTA → Acb DAergic neurons appear to play a role in these effects, which underscores the stress paradigm-specific nature of the molecular, cellular and circuit mechanisms involved in stress-induced depression-related behaviors." (PMID 36499323, 2022). "No significant BDNF rhythm was found in the plasma, frontal cortex or SCN of SP acclimated animals, which also had higher insulin levels, significantly higher glucose levels in the OGTT, and significantly higher anxiety- and depression-like behaviors compared with animals acclimated to NP." (PMID 36160856, 2022). "However, the positive effect of omega-3 FA supplementation on BDNF levels was seen only in depressed patients diagnosed with depressive disorder, but not in patients with mixed anxiety and depressive disorder (evaluated through a correlation between EPA, DHA, and BDNF)." (PMID 33801688, 2021). "Additionally, patients that were treated with ayahuasca, and not with placebo, presented a negative significant correlation between BDNF levels and MADRS scores at D2: higher serum BDNF levels were correlated with lower depression symptomatology after the session with ayahuasca." (PMID 31231276, 2019). "However, patients with UC were not evaluated for depression using both CES-D and BDNF levels." (PMID 29321655, 2018). "In addition, using postmortem tissues, we reported correlations between BDNF propeptide in the brain and spleen, and a negative correlation between CSF1R and transcription factor PU.1 (SPI1), suggesting a role for the brain–spleen axis in psychiatric disorders such as depression." (PMID 33963284, 2022). "In addition to the decreased contents and expression of BDNF and its cognate TrkB receptor, the levels of nerve growth factor (NGF) and its receptor TrkA proteins and mRNAs are also lower in the hippocampus of suicide victims with major depression as compared to nonpsychiatric individuals." (PMID 24999483, 2014).
Cognitive impairment (1,169 papers, 2009 to 2026). Abnormal cognition is characterized by deficits in thinking, reasoning, or remembering. "BDNF is essential for neuronal survival and plasticity andits dysregulation has been linked to cognitive impairment and mood disorders." (PMID 40822814, 2025). "Extensive research has demonstrated that alterations in BDNF levels are associated with the risk of schizophrenia onset, symptom severity, and cognitive impairments." (PMID 40082848, 2025). "BDNF is widely regarded as a significant biomarker in the realm of cognitive impairment, with numerous studies consistently demonstrating diminished BDNF levels in patients exhibiting cognitive deficits associated with mild cognitive impairment (MCI)." (PMID 40291844, 2025). "Lactiplantibacillus plantarum C29-fermented soybean has been shown to be a safe and effective nutritional supplement for improving cognitive function in individuals with mild cognitive impairment, with effects associated with increased serum levels of BDNF." (PMID 41415845, 2025). "LGG supplementation significantly alleviated sepsis-caused decreases in hippocampal BDNF expression and p-TrkB phosphorylation levels, preserving neuronal survival and improving cognitive impairments in mice with sepsis." (PMID 40697274, 2025). "A recurring finding was the elevation of pro-inflammatory cytokines (i.e., IL-1β, IL-6, TNF-α) together with reduced BDNF levels, frequently associated with cognitive deficits in both healthy and tumor-bearing models." (PMID 41155372, 2025). "The studies included in this research demonstrated that acupuncture activates the PKA/CREB and BDNF/TrkB signaling pathways, thereby mitigating cognitive impairments caused by sleep disorders." (PMID 40177248, 2025). "Schizophrenia: The Val66Met polymorphism diminishes activity-dependent BDNF release resulting in synaptic deficits and cognitive impairments." (PMID 40362507, 2025). "Future studies should explore the therapeutic potential of BDNF modulation or TrkB agonists to address cognitive impairments associated with trypanosome infections." (PMID 40977748, 2025). "In humans, rare mutations or deletions in BDNF are associated with early onset obesity, hyperphagia, and cognitive impairments." (PMID 41082226, 2025). "Comparable BDNF levels were measured in a study on 660 ischemic stroke patients, with BDNF higher than 38.61 ng/ml inversely associated with severity of post stroke cognitive impairment." (PMID 41447407, 2025). "Due to the close association between cognitive impairment and nerve damage, brain-derived neurotrophic factor (BDNF) is essential for neuronal growth and synaptic plasticity." (PMID 40534913, 2025). "It has been shown that CAD patients had low serum levels of brain‐derived neurotrophic factor (BDNF), which has a cognitive enhancer effect and negatively correlates with the risk of cognitive impairment and Alzheimer's disease (AD)." (PMID 39828641, 2025). "A decrease in serum BDNF levels has been linked to cognitive impairments across a range of disorders including Alzheimer’s disease and MCI." (PMID 40291844, 2025). "This aligns with the current understanding that Aβ pathology can downregulate CREB/BDNF signaling, contributing to synaptic loss and cognitive impairment." (PMID 40871065, 2025). "BDNF is essential for neuronal survival, growth, and plasticity, and its deficiency is associated with neurodegenerative diseases and cognitive deficits." (PMID 40220083, 2025). "Previous research has demonstrated that serum BDNF levels are significantly diminished in patients with dementia, with severe cognitive impairment being closely associated with reduced BDNF concentrations." (PMID 40852521, 2025). "Studies have demonstrated that B[a]P-treated mice exhibited increased levels of Dnmt in the cerebral cortex, causing hypermethylation of the BDNF gene and decreasing BDNF in the brain, resulting in cognitive deficits in mice." (PMID 39997934, 2025).